CRP (C-reactive protein)
Diseases named in the same sentence as CRP in open-access papers (continued):
Sharing a sentence is not in itself a finding about the gene and the disease.
lymphopenia (continued). "Common laboratory findings encompass leukopenia (lymphopenia), increased C-reactive protein (CRP), lactate dehydrogenase and elevated transaminases." (PMID 39337343, 2024). "In the total sample, cfDNA was the only NET marker that correlated with typical clinical severity factors, such as lymphopenia, neutrophil/lymphocyte ratio, C-reactive protein, lactate dehydrogenase levels, and baseline SaO2." (PMID 38243237, 2024). "Particularly; lymphopenia, high NLR, thrombocytopenia, and elevated CRP level are all significantly associated with poor prognosis." (PMID 39659435, 2024). "In our research, we concluded that there is a statistically significant difference between the groups for the non-specific inflammation parameter CRP and lymphocytes (increased CRP values and lymphopenia) in the group with active LN." (PMID 38496018, 2024). "The co-occurrence of lymphopenia alongside elevated CRP levels is indicative of a cytokine storm, a severe form of immune dysregulation characterized by excessive inflammation." (PMID 39679195, 2024). "Lymphopenia, neutrophilia, and thrombocytopenia, as well as increased levels of CRP, AST, creatinine, ferritin, AST, troponin I, urea, magnesium, and potassium served as prognostic markers and were associated with patient mortality." (PMID 39281667, 2024). "Laboratory evaluation showed lymphopenia (0.22 × 109/L, normal values 1.00–3.50 × 109/L) and a C-reactive protein level of 81 mg/L." (PMID 38813383, 2024). "Our results confirm that lymphopenia is most frequently present in patients with systemic involvement and that other biological markers such as serum calcium, CRP, ACE, and the lumbar puncture analysis are non‐specific." (PMID 39279263, 2024). "These patients present with marked lymphopenia or thrombopenia, increased inflammatory indices and acute phase proteins including CRP, ferritin and d-Dimers." (PMID 39595974, 2024). "Specifically, laboratory tests that should be prioritized to determine patient risk of developing severe COVID-19 pneumonia, include lymphopenia, NLR, thrombocytopenia, CRP, D-Dimer, creatinine, LDH, CK, troponin and NT-Pro-BNP." (PMID 39659435, 2024). "Laboratory abnormalities include elevated C-reactive protein (CRP), liver enzymes, D-dimer, lymphopenia, neutropenia, thrombocytopenia, and coagulopathy." (PMID 38256558, 2024). "Laboratory tests performed during the flares revealed lymphopenia and increased levels of C-reactive protein and ferritin." (PMID 38343641, 2024). "SARS‐CoV‐2 infection is also associated with lymphopenia, prolonged prothrombin time (PT), high levels of LDH, ALT, AST, D‐dimer, C‐reactive protein (CRP), and troponin, along with neutrophilia and eosinophilia." (PMID 38384141, 2024). "The most frequent laboratory deviations in patients with COVID-19 infection are lymphopenia, neutrophilia, thrombocytopenia, and elevated levels of serum C-reactive protein (CRP)." (PMID 38982355, 2024). "Specific markers, such as lymphocytopenia, neutropenia, elevated serum liver enzymes, LDH, CRP, and ferritin, have been associated with an elevated risk of severe disease." (PMID 37712883, 2024). "This was followed by increased ferritin in 71.4%, elevated troponin in 66%, elevated ESR in 59.7%, lymphopenia in 51%, and increased CRP in 49.7%." (PMID 39570835, 2024). "Laboratory markers associated with increased risk for severe disease include lymphocytopenia, neutrophilia, and elevated serum ALT, AST, LDH, CRP, and ferritin." (PMID 37510752, 2023). "High neutrophil count, lymphopenia, high C-reactive protein (CRP), Lactate dehydrogenase (LDH), Ferritin, and IL-6, for example, were all shown to be predictors of disease severity in various studies world-wide." (PMID 37497238, 2023). "The magnitude of abnormality of immune and inflammatory markers at baseline—lymphopenia, neutrophilia, a high NLR, elevated levels of CRP and PCT, and low levels of IgG and IgM—was associated with worse outcomes." (PMID 37946226, 2023).
lymphopenia (continued). "Laboratory results identified white blood count (WBC) values of 12.307±8.4211/μL, neutrophilia 10.381±7.924/μL, and lymphopenia 0.958±0.783/μL and high values of CRP= 106.810 (5.660–353.300) mg/L." (PMID 37969882, 2023). "Blood profile showed lymphopenia (580 cells/mm3), mild hyperbilirubinemia (0.47 mg/dL), and a serum C-reactive protein (CRP) concentration within normal limits (0.9 mg/dL)." (PMID 36966282, 2023). "The most frequent laboratory alterations are elevated C-reactive protein (CRP), hepatic enzymes and mild lymphopenia and neutrophilia." (PMID 37360613, 2023). "Along with neutrophil count, lymphopenia, N/L ratio, and CRP, cfDNA was the only persistent and significantly higher biomarker in the non-survivors during the 3 disease phases." (PMID 37147677, 2023). "The correlation between cfDNA and LDH was not robust, and cfDNA correlated better than LDH with common severity markers (neutrophilia, lymphopenia, CRP, SaO2, SaO2/FiO2), especially in the CI group and late inflammatory phases." (PMID 37147677, 2023). "Biologically, in the present study, several organ dysfunctions and biological abnormalities were noted in the inflammatory (very high CRP, neutrophilia, severe lymphopenia) and metabolic (hyperglycemia, hepatic cytolysis, hypercholesterolemia) fields." (PMID 37474897, 2023). "Most of the inflammatory markers, like D-dimer, ferritin, CRP, and other hematologic parameters, were above baseline together with lymphopenia (mean percentage = 9.0 ± 1.0), but had normal other hematologic parameters." (PMID 38004749, 2023). "Patients can also present normal or abnormal leukocyte counts, lymphopenia, or thrombocytopenia, with extended activated thromboplastin time, and elevated C-reactive protein (CRP)." (PMID 36597151, 2023). "As noted in the text, some of the poor laboratory prognostic factors include high D-Dimer, lymphopenia, thrombocytopenia, CRP." (PMID 37545952, 2023). "Laboratory exams further showed increased neutrophil counts, lymphopenia, hypertriglyceridemia and hyperfibrinogemia, D Dimer 114.9 (nv <0.5), and CRP 160 mg/l (nv <0.5)." (PMID 37435083, 2023). "Some studies suggest associations between lower Ct values on admission samples and disease severity markers, including elevated levels of IL-6, LDH, CRP, lymphopenia and an elevated neutrophil/lymphocyte ratio." (PMID 37213664, 2023). "When an indeterminate IGRA result was used as the dependent variable, age, a solid malignancy, autoimmune disease, corticosteroid use, acute infection, lymphopenia, CRP, and hypoalbuminemia were independent predictors." (PMID 37420251, 2023). "The numbers of total leukocytes, lymphocytes, and thrombocytes were significantly increased, while the CRP levels were reduced one week after diagnosis, indicating the improvement of lymphopenia and thrombocytopenia, and a decrease in inflammation." (PMID 37174682, 2023). "We found that most patients with psittacosis had normal WBC counts, lymphopenia, and elevated levels of CRP, D-dimer, and LDH, consistent with previously published studies." (PMID 38264732, 2023). "Those levels also positively correlated with lymphopenia and the pro-inflammatory factors interleukin1β (IL1β), IL6, and C-reactive protein, markers associated with the anti-viral inflammatory response." (PMID 38313435, 2023). "Our findings align with those of other authors, who reported the association of AKI with high ferritin values, CRP, and severe pulmonary changes or with high levels of LDH, procalcitonin, or ASAT and lymphopenia." (PMID 37685436, 2023). "These patients also showed variation of some of the other haematological parameters tested at admission: increased IL-6, IL-10 and CRP, leucocytosis, neutrophilia, and lymphopenia." (PMID 37215142, 2023). "Both groups received standard therapy and they were monitored on days 3, 7, and 14 after the beginning of the therapy for clinical symptoms’ improvement, quantitative CRP, lymphopenia, CBC, and SpO2." (PMID 37654997, 2023).
lymphopenia (continued). "Other identified risk factors were age 6–12 years and especially 13–20 years, non-Hispanic Black ethnicity, shortness of breath, abdominal pain, thrombocytopenia, lymphocytopenia, and increased levels of CRP, troponin, ferritin, D-dimers or IL-6." (PMID 37046304, 2023). "MIS biomarkers including neutrophilia, lymphocytopenia, high neutrophil-to-lymphocyte ratios, thrombocytopenia, elevated CRP, PCT, LDH, D-dimer, and ferritin variably and significantly correlated with each other, as well as with impaired PaO2 and SaO2." (PMID 36830885, 2023). "Lymphopenia, neutrophilia, and elevated inflammatory markers such as C-reactive protein (CRP), erythrocyte sedimentation rate (ESR), D-dimers, procalcitonin, fibrinogen and ferritin are detected in most patients with MIS-C and correlate with disease severity." (PMID 36982783, 2023). "Lv17/WB/Rie1 triggered an inflammatory response, with increased levels of CRP and pro-inflammatory cytokines, and induced lymphopenia, thrombocytopenia and a decline in red blood cell (RBC) parameters, although this was transitory." (PMID 37515092, 2023). "Most patients with Chlamydia psittaci pneumonia had a normal white blood cell count, lymphopenia, and varying degrees of elevated CRP and D-dimer levels." (PMID 38264732, 2023). "In the current analysis, the lowest mortality relative to placebo was associated with the use of trimodulin in sCAP patient subsets with high CRP, low IgM, and/or lymphopenia and/or high NLR." (PMID 37946226, 2023). "Significant changes in inflammatory markers such as C-reactive protein (CRP), procalcitonin, D-dimer, and lymphopenia have been described in people with pre-existing type 2 diabetes (T2DM), and notably in poorly managed T2DM with hyperglycemia." (PMID 36851087, 2023). "A total of 8 patients had leukopenia (<4.3 × 109/L), 11 patients had lymphopenia (<1.1 × 109/L), 5 patients had thrombocytopenia (<140 × 109/L), and 21 patients had increased blood C-reactive protein (CRP) levels (>5.0 mg/mL)." (PMID 37174682, 2023). "Seventeen patients suffered a severe attack, with an oxygen saturation < 94% (54.8%), 26 patients had lymphopenia, evident in the complete blood count (83.9%), 22 had a D-Dimer > 0.5 mg/L (71%), and 29 (93.6%) had a high CRP." (PMID 37923735, 2023). "In the evaluation of hospitalization, CRP (>50 mg/L), d-dimer (>550 μg/mL), ferritin (>500 ng/mL), fibrinogen (>400 mg/dL) and lymphopenia (lymphocytes < 1 × 103/μL) values were especially considered together with the symptoms." (PMID 37112613, 2023). "Similarities included resolution of lymphopenia and neutrophilia and a rapid decrease in the serum concentrations of CRP, TNF-α, IL-6, IFN-γ, IL-10, TNFR-1, and IP-10 following treatment with Allocetra-OTS." (PMID 37600829, 2023). "Patients with MIS-C had a higher neutrophil count, more CRP, and ferritin, as well as profound lymphopenia and hyponatremia compared with those with KD and TSS." (PMID 36984627, 2023). "On a chest X-ray, it was discovered that there was one case of leucopenia, 25 cases of lymphopenia, 38 cases of lymphocytosis, 72 cases of CRP positivity, and 43 cases of pneumonitis." (PMID 37900461, 2023). "Severity of the disease is evaluated by different biological parameters such as lymphopenia, blood oxygen saturation, C-reactive protein (CRP) levels and D-dimer levels." (PMID 36851633, 2023). "Among the most common abnormal laboratory findings were lymphopenia, elevated CRP, and D-dimer level." (PMID 36085364, 2023). "In general, it stands out that the majority of patients had lymphopenia, mild neutrophilia, as well as elevated C-reactive protein (CRP), ferritin, lactate dehydrogenase (LDH), fibrinogen and interleukin-6 (IL-6)." (PMID 37892366, 2023). "Human COVID-19 disease has been marked by alterations in hematology and serum chemistry markers, including lymphopenia and increases in C-reactive protein (CRP)." (PMID 35632755, 2022).
lymphopenia (continued). "In our study, when the laboratory parameters of the patients were analyzed, lymphopenia (p≤0.001), elevated CRP (p=0.05), D-dimer (p=0.05), and ferritin (p=0.006) were significantly different in the mortal and non-mortal groups." (PMID 36379528, 2022). "Then, we calculated and compared the fold changes of these various clinical indicators per day in these two groups with lymphopenia, CRP elevation, fibrinogen elevation, and D-dimer elevation, respectively." (PMID 35304437, 2022). "These include lymphopenia, thrombocytopenia, and elevated levels of CRP, procalcitonin, LDH, and D-dimer." (PMID 35207812, 2022). "Laboratory investigations were significant for lymphopenia of 0.32×103/mm3, D-dimer of 1484 ng/mL, CRP 300 mg/L, LDH 756 U/L, and ferritin 7500 ng/mL." (PMID 36505163, 2022). "The mortality rate of patients with lymphopenia (p≤0.001), elevated CRP (p=0.05), elevated D-dimer (p=0.05), and ferritin (p=0.006) on admission were significantly higher than the other patients." (PMID 36379528, 2022). "During this period, more severe hematological abnormalities, such as lymphopenia, neutrophilia, neutropenia, and thrombocytopenia develop, and immunological parameters such as IL-6, CRP, and PCT, increase in severe cases." (PMID 35204599, 2022). "Lymphocytopenia, d‐dimer, LDH, and CRP levels, which were significantly linked to the severity of COVID‐19, were the prognostic biomarkers to predict the disease severity." (PMID 35894709, 2022). "Laboratory results revealed microcytic anemia, lymphopenia, thrombocytosis, elevated CRP and ESR, hyponatremia, high fibrinogen level, elevated D-dimers, increase in amylase and lipase." (PMID 35628892, 2022). "Lethality also corresponded with elevated CRP along with lymphopenia, thrombocytopenia, and neutrophilia." (PMID 35622847, 2022). "Lymphocytopenia, tachycardia, tachypnea, elevated CRP,d‐dimer, serum ferritin, LDH, and decreased SP02 were significantly observed in cases with complicated severe acute respiratory syndrome coronavirus 2 (p < .05 for all)." (PMID 35894709, 2022). "In terms of laboratory parameters, children with PIMS were commonly found with increased inflammatory markers, consisting of high C-reactive protein (CRP) in 94% of the cases, but also neutrophilia in 83% or lymphopenia in 50% of the patients." (PMID 36138657, 2022). "According to the laboratory findings, the most commonly reported disorders were increased CRP, lymphopenia, decreased white blood cells, and increased liver enzymes." (PMID 36187739, 2022). "Lymphopenia and increase of C-reactive Protein (CRP) are the laboratory parameters’ modifications most frequently found." (PMID 35736656, 2022). "Laboratory testing showed leukopenia, lymphopenia, and the elevation of both C-reactive protein (CRP) and erythrocyte sedimentation rate (ESR)." (PMID 35127185, 2022). "At the laboratory analysis lymphopenia, elevated erythrocyte sedimentation rate, C-reactive protein, lactate dehydrogenase, interleukin-6, serum ferritin, and D-dimer anomalies were found in all the patients." (PMID 36296214, 2022). "Inflammatory markers (CRP, D-dimer, and ferritin) were elevated and so was the incidence of lymphopenia." (PMID 35547540, 2022). "Common laboratory findings during active disease include lymphopenia, which is proportional to the severity of disease, hyperfibrinogenaemia, hyperferritinaemia and increased d-dimer values and C-reactive protein (CRP)." (PMID 35328649, 2022). "For consumption thrombocytopenia, the risk factors are advanced age, male gender, high APACHE II score, neutropenia, lymphopenia, elevated CRP, and a low PaO2/FiO2 ratio." (PMID 35207365, 2022). "Routine laboratory markers reveal lymphopenia (especially T cell depletion), high serum ferritin, D-dimers, C-reactive protein (CRP) and cytokines, including IL-1b, IL-6, and TNF-α." (PMID 35891232, 2022).
lymphopenia (continued). "Her laboratory abnormalities showed lymphopenia, high levels of ferritin, D-dimer, CRP, AST, ALT, and BUN, and a low serum albumin level." (PMID 36553314, 2022). "Many researchers suggested that spontaneous pneumothorax was possible in patients with high C-reactive protein, severe lymphopenia, high D-dimer, high lactate dehydrogenase and ferritin, or high viral load." (PMID 35911291, 2022). "CRP level was prominently higher in the severe group and those patients had a higher percentage of lymphopenia (75%) and thrombocytopenia (53.1%) events compared to patients with moderate and mild disease (p < 0.0001, p = 0.0001 and p = 0.0005, respectively)." (PMID 35910207, 2022). "At the same time, children with MIS-C had pronounced lymphopenia, with elevated acute phase reactants (CRP, ESR and NT-pro-brain natriuretic peptides or pro-BNP)." (PMID 35457086, 2022). "Individuals with variants from multiple IUIS classes had increased odds of positive blood, respiratory, or urine culture and increased odds of hyperferritinemia, lymphopenia, thrombocytopenia, and CRP > 10 mg/dl." (PMID 34973142, 2022). "Analysis revealed leukopenia with lymphopenia, thrombocytopenia, moderate D-Dimer, transaminases, C-reactive protein (CRP), and elevation of LDH." (PMID 35568905, 2022). "Lymphopenia, increased D-dimer, hypersensitive C-reactive protein (hsCRP), and interleukin-6 (IL-6) were elevated in them." (PMID 35103220, 2022). "As in many series, age and comorbidities, neutrophilia, lymphopenia and high CRP are predictors of mortality." (PMID 34761389, 2022). "Laboratory examinations showed elevated CRP (6/9), lymphopenia (5/9), alanine aminotransferase (ALT), and aspartate aminotransferase (AST) (3/9)." (PMID 36756491, 2022). "This categorization has been shown to have a significant correlation with lymphopenia, CRP, ferritin, D-dimer, length of hospitalization, oxygen requirement, and ICU admission." (PMID 35382199, 2022). "The most common inflammatory marker to be elevated was CRP, 41(23%) had elevated CRP, lymphopenia was only seen in 26 (14%) patients and only 5 (3%) patients had elevated procalcitonin." (PMID 36619504, 2022). "A systematic review on the clinical characteristics of COVID19 in children, showed that the main clinical features were mild symptoms including fever, cough, and rhinorrhea, with lymphopenia and increased D-dimer and CRP levels." (PMID 36583110, 2022). "Mechanical ventilation, intensive care in addition to lymphopenia, higher rates of neutrophils/lymphocytes, and elevated CRP and troponin levels were most common among PMIS patients compared to those with mild and moderate/severe disease." (PMID 36118201, 2022). "In univariate analysis, older age, comorbidity, lymphopenia, high levels of CRP, ESR, lactate, estimated glomerular filtration rate (e-GFR), low levels of albumin, and fewer vaccination doses are all associated with the severity of Omicron infection." (PMID 36146487, 2022). "As a result of this connection, many biomarkers of aging have been used in studies of inflammation states; levels of C-reactive protein (CRP), interleukin-6, ferritin, and lymphopenia have been mentioned." (PMID 35455991, 2022). "In a systematic review of patients with MIS-C authors found that inflammatory markers were raised in most of the cases, including neutrophilia, elevated CRP level and lymphopenia." (PMID 36254726, 2022). "This was the group with higher capillary glycemia, creatinine, lower phosphate levels, higher C-reactive protein, neutropenia and lymphopenia." (PMID 36010281, 2022). "Laboratory tests were normal, except for lymphopenia (0.61 x 109/l) and a mild elevation of C-reactive protein (CRP), at 54 mg/l (normal range: 0–5)." (PMID 35852114, 2022). "The majority (66.7%) of the children had positive SARS-CoV-2 serology and elevated inflammatory markers (C-reactive protein, procalcitonin, ferritin, D-dimer, and fibrinogen), lymphopenia, and thrombocytopenia." (PMID 35172274, 2022).